RP2 (RP2 activator of ARL3 GTPase)
Diseases named in the same sentence as RP2 in open-access papers (continued):
Sharing a sentence is not in itself a finding about the gene and the disease.
preeclampsia (1 paper, 2014). Preeclampsia is a hypertensive disorder of pregnancy that is characterized by new-onset hypertension with proteinuria presenting after 20 weeks of gestation, and depending on mild or severe forms may initially present with severe headache, visual disturbances, and hyperreflexia. "In the present study we found that RP1/RP2 and RP2/RP2 genotypes and RP2 allele could be risk factors in predisposing to preeclampsia in our population." (PMID 24877103, 2014). "Moreover, the RP2 allele was found more prevalent in preeclampsia patients in comparison with healthy subjects (18.8% versus 6.7%) and may enhance the risk of preeclampsia by 3.1-fold." (PMID 24877103, 2014).
renal carcinoma (1 paper, 2022). A carcinoma arising from the epithelium of the renal parenchyma or the renal pelvis. "The protein expression of RP2 was nearly not detected in renal cancer, whereas low expression of that was found in normal kidney tissues." (PMID 36035369, 2022).
retinitis (1 paper, 2014). Inflammation of the retina. "Using computational analysis, we revealed an extragenic tandem GAAA repeat 230-bp from the landmark CpG island of the human X-linked retinitis pigmentosa 2 RP2 promoter whose 5meCpG status correlates with XCI." (PMID 25078280, 2014).
cancer (3 papers, 2013 to 2023). A tumor composed of atypical neoplastic, often pleomorphic cells that invade other tissues. "The associated cancer functional states of hsa-mir-21 predicted target genes (RP2, NFIA, SPRY1 and TGFBI) was first revealed." (PMID 36035369, 2022). "Simultaneously, the high expression of immune checkpoints in RP2 overexpressed cancer tissues predicts a strong immune evasion ability of tumor tissues compared to normal cells." (PMID 37602882, 2023). "Cancer single-cell analysis indicated expression of RP2 was related to the Inhibition of cancer Invasion." (PMID 36035369, 2022). "Inhibition of RP2, although ultimately fatal to all cells, can allow for a therapeutic window by selectively affecting molecules essential to cancer cell survival." (PMID 23767415, 2013). "We hypothesised that dormant cancer cells, already low in RNA, might be sensitive to apoptosis induced by RNA Polymerase II (RP2) inhibitors that further reduce RNA synthesis." (PMID 23767415, 2013). "The transcriptional expression of RP2, NFIA, SPRY1 and TGFBI in four cancer stages was significantly higher than that of the normal." (PMID 36035369, 2022). "The transcriptional expression of RP2, NFIA and SPRY1 in four cancer grades was significantly higher than that of the normal." (PMID 36035369, 2022).
infection (3 papers, 2015 to 2022). The state of being infected such as from the introduction of a foreign agent such as serum, vaccine, antigenic substance or organism. "The rP18-infected animals experienced significantly more bodyweight loss and longer duration of fever than animals infected with the avirulent rP2 or with PBS injection (mock infection), which are consistent with our previous observations." (PMID 35758052, 2022). "We found that, when averaged as a group, the rP18-infected animals had significantly increased hearing threshold levels post infection (when compared to their baseline levels) than the mock or rP2-infected groups." (PMID 35758052, 2022).
retinal disorder (3 papers, 2011 to 2021). Any disease or disorder of the retina. "Additional investigations are necessary to determine the involvement of these pathways in cone dysfunction in RP2-associated as well as other retinopathies." (PMID 31024631, 2019). "As the human RP2 mRNA could rescue the rp2-MO associated retinopathy phenotype, we utilized the rp2-MO zebrafish as an assay system to investigate the pathogenic potential of selected nonsynonymous amino acid variations observed in patients." (PMID 21738648, 2011). "The retinopathy phenotype could be rescued by expressing the wild-type human RP2 protein." (PMID 21738648, 2011). "We found that the human mRNA could efficiently rescue the retinopathy phenotype associated with suppression of rp2, whereas mRNA encoding GFP alone did not result in a rescue." (PMID 21738648, 2011).
tumor (3 papers, 2000 to 2025). "We noticed that RP2 mRNA expression was upregulated in patients above 60, with higher tumour grade, unmutated group of IDH and in the non-coding 1P/19Q." (PMID 37602882, 2023). "Therefore, we speculated that CD8+T cells could not play its role in killing tumor cells when RP2 was highly expressed." (PMID 37602882, 2023).
RP2 also shares sentences with these, for which no sentence is quoted: Leber congenital amaurosis (3 papers); macular dystrophies (2); melanoma (2); prostate carcinoma (2); Usher syndrome (2); X-linked retinoschisis (2); achromatopsia (1); acute lymphoblastic leukaemia (1); adenocarcinoma (1); autosomal recessive retinitis pigmentosa (1); benign prostatic hyperplasia (1); breast carcinoma (1); corneal dystrophy (1); emphysema (1); head and neck cancer (1); Joubert syndrome (1); Norrie disease (1); Nystagmus (1); osteosarcoma (1); pancreatic ductal adenocarcinoma (1); retinal ciliopathy (1); retinal detachment (1); retinitis pigmentosa 2 (1); Stargardt disease (1); Stickler syndrome (1); X-linked familial exudative vitreoretinopathy (1).